STIM1 (stromal interaction molecule 1)
Diseases named in the same sentence as STIM1 in open-access papers (continued):
Sharing a sentence is not in itself a finding about the gene and the disease.
ischemia (4 papers, 2019 to 2022). A hypoperfusion of the BLOOD through an organ or tissue caused by a PATHOLOGIC CONSTRICTION or obstruction of its BLOOD VESSELS, or an absence of BLOOD CIRCULATION. "Even though ER Ca2+ depletion represents an undisputed factor of neuronal cell injury, the modulation of the STIM1/ORAI1 complex during ischemia is still under scrutiny." (PMID 35163310, 2022). "The suppression of STIM1 in the early stage of ischemia attenuates neuronal death by inhibiting SOCE-induced neuronal apoptosis." (PMID 31075835, 2019). "Another study suggested that STIM1 also contributes to pathological changes that occur in ischemia." (PMID 31075835, 2019). "Additionally, STIM1 siRNA injection significantly improved neurological functions and decreased neuronal Ca2+ levels following ischemia, suggesting a role for STIM1 in mediating ischemia-induced brain damage." (PMID 35821821, 2022). "For capacitive Ca2+ entry (CCE) and Ca2+ overload induced by ischemia, the regulating effect of STIM2 is more significant than STIM1 in neuronal hypoxic cell death." (PMID 34408630, 2021). "Intracellular high Ca2+ concentration due to the increased STIM1 and ORAI1 levels that occur in global ischemia rats dropped significantly with the injection of STIM1 siRNA, and then the rats had fewer neurological deficits compared with control." (PMID 34408630, 2021). "In a model of hepatic ischemia/reperfusion (I/R) injury, mice lacking STIM1 exhibited an attenuated cellular inflammation and apoptosis compared to controls." (PMID 35821821, 2022).
rhabdoid tumor (4 papers, 2016 to 2024). An aggressive malignant embryonal neoplasm usually occurring during childhood. "A study of STIM1 indicated that the gene locus encoding STIM1 on chromosome 11p15 was deleted in human rhabdomyosarcoma and rhabdoid tumor cell lines." (PMID 27013185, 2016). "On the other hand, overexpression of STIM1 inhibits cell growth of rhabdoid tumor or rhabdomyosarcoma cell lines, suggesting that the protein amount of STIM1 needs to be strictly regulated for proper cell proliferation." (PMID 39128711, 2024). "For example, STIM1 was identified to play a potential role as a tumor growth suppressor in G401 rhabdoid tumor, rhabdomyosarcoma and rodent myoblast cell lines." (PMID 31564210, 2019).
rhabdomyosarcoma (4 papers, 2016 to 2024). A rare aggressive malignant mesenchymal neoplasm arising from skeletal muscle. "Ectopic overexpression of STIM1 in vitro could induce morphologic changes in rhabdomyosarcoma cells and ultimately lead to cell death." (PMID 27013185, 2016).
Sepsis (4 papers, 2015 to 2023). Sepsis is defined as life-threatening organ dysfunction caused by a dysregulated host response to infection. "Aberrant STIM1 and Orai1 glycosylation have been reported in a number of disorders, for instance, it has been detected in myopathies with tubular aggregates and in sepsis-induced myocardial depression." (PMID 36612199, 2022). "STIM1 is upregulated in endothelial cells during sepsis, and its expression was shown to depend on cooperation between NFκB and p38 MAPK." (PMID 32817784, 2020). "To further corroborate the in vitro findings we subjected Stim1−/− bone marrow chimeric mice to different in vivo models of LPS-induced sepsis, Thg-induced peritonitis, and AIHA." (PMID 26417434, 2015). "Since these reactions are not largely dependent on STIM1 but are reduced in BTP2-treated mice, STIM2 may be a possible target through which BTP2 suppresses cell migration and provides protection against cytokine-mediated effects in sepsis." (PMID 26417434, 2015).
Skeletal myopathy (4 papers, 2008 to 2025). "In murine skeletal muscle STIM1 expression is also required for NFAT-mediated activation of gene expression during myogenesis, with STIM1-deficiency causing skeletal myopathy." (PMID 18950512, 2008). "The SOC Ca2+ sensor STIM1 is expressed in skeletal muscle, where its absence leads to decreased force, accelerated fatigue, and eventual perinatal death in mice due to skeletal myopathy." (PMID 32009985, 2019). "Mice lacking STIM1 die of perinatal skeletal myopathy, indicating that STIM1-dependent Ca2+ signaling is required for myogenesis." (PMID 40507171, 2025). "Toluidine blue–stained sections from 3-month-old STIM1+/D84G mice identified abnormally shaped, pale fibers, necrotic fibers, and expansion of the extracellular matrix — nonspecific findings often seen in skeletal myopathies." (PMID 38300705, 2024).
Splenomegaly (4 papers, 2017 to 2020). Abnormal increased size of the spleen. "Dissection of male Stim1/2Foxp3 mice revealed splenomegaly and lymphadenopathy with significantly enlarged submandibular, inguinal, and axillary LNs compared to WT littermate controls, whereas mesenteric LNs were less enlarged." (PMID 30862784, 2019). "Knockout of the ER Ca2+ sensors STIM1 and STIM2 in mice resulted in splenomegaly and reductions in proliferation, cytokine secretion and NFAT nuclear translocation in T cells upon TCR engagement." (PMID 29445164, 2018).
thyroid cancer (4 papers, 2021 to 2023). "Taken together, our data suggest that STIM1 is a potential diagnostic and therapeutic target for treatment of thyroid cancer." (PMID 34155535, 2021). "Furthermore, we show that STIM1-KD increases the susceptibility of thyroid cancer ML-1 cells to drugs used for treatment of thyroid cancer, reinstates the expression of thyroid stimulating hormone receptor (TSHR), thyroid specific proteins and increased iodine uptake." (PMID 34155535, 2021). "Recently STIM1 and Orai1 have been shown to be upregulated in thyroid cancer patient tissue samples as well as in thyroid cancer cell lines compared with primary thyroid cells." (PMID 38089882, 2023). "We report that the expression of STIM1 is upregulated in all thyroid cancer cell lines studied compared to primary thyroid cells." (PMID 34155535, 2021). "A higher STIM1 expression in follicular thyroid cancer tissues compared to the papillary thyroid cancer tissues datasets further suggests that STIM1 is important in the development of an aggressive thyroid cancer phenotype." (PMID 34155535, 2021). "The results showed an increased STIM1 staining in all types of thyroid cancer patient samples, compared to respective patient’s normal thyroid tissue adjacent to the tumor, or with healthy subjects’ normal thyroid tissue sections." (PMID 34155535, 2021). "We have shown here using different approaches and gene downregulation in thyroid cancer cells that calcium signaling and the STIM1 protein play an important function in driving thyroid cancer cell proliferation and invasion." (PMID 34155535, 2021). "The SOCE is decreaed in STIM1 knockdown and Orai1 knockdown thyroid cancer cells." (PMID 38089882, 2023). "We have recently shown that downregulation of calcium signals e.g., by knocking down the transient receptor potential canonical channel 1 (TRPC1), or the stromal interacting molecule 1 (STIM1), dramatically decreases invasion and proliferation of thyroid cancer cells." (PMID 36497320, 2022). "STIM1 protein was upregulated in thyroid cancer tissue, compared to normal tissue." (PMID 34155535, 2021). "Notably, STIM1 was upregulated in all thyroid cancer patient tissue samples investigated, as compared with normal thyroid tissue." (PMID 34155535, 2021). "The differential STIM1 and ORAI1 gene expression analysis data clearly showed an upregulation of these genes in most of the thyroid cancer tissues compared to normal thyroid tissues datasets." (PMID 34155535, 2021). "We show here that, especially STIM1, but to some extent also ORAI1, are upregulated in several thyroid cancers cell lines, compared with normal thyroid cells." (PMID 34155535, 2021). "The expression of both STIM1 and ORAI1 genes was significantly upregulated in both the papillary and combined thyroid cancer tissues (Total), compared to tumor adjacent normal thyroid tissues (NT)." (PMID 34155535, 2021). "The expression and function of STIM1 and ORAI1 in thyroid cancer progression and invasion have, however, remained elusive." (PMID 34155535, 2021). "We show that STIM1 and ORAI1 expression is elevated in thyroid cancer cell lines, compared to primary thyroid cells." (PMID 34155535, 2021). "STIM1 and ORAI1 gene expression was evaluated in thyroid tumor tissues (n = 502) versus normal thyroid solid tissues (n = 58) datasets in the TCGA Thyroid Carcinoma cohort." (PMID 34155535, 2021). "Knock-down of STIM1 or ORAI1 attenuated SOCE, reduced invasion, and the expression of promigratory sphingosine 1-phosphate and vascular endothelial growth factor-2 receptors in thyroid cancer ML-1 cells." (PMID 34155535, 2021). "Thus, both STIM1 and ORAI1 are important regulators of thyroid cancer cell invasion." (PMID 34155535, 2021). "Thus, both STIM1 and ORAI1 are important in regulating SOCE in thyroid cancer cells." (PMID 34155535, 2021).
allergic disease (3 papers, 2019 to 2025). An immune response that occurs following re-exposure to an innocuous antigen, and that requires the presence of existing antibodies against that antigen. "Given that SOCE via STIM1 promotes responses of FcεRI and MRGPRX2, two important mast cells receptors that mediate allergy in humans; future studies designed to characterize this mechanism further may lead to the development of novel therapeutic approaches for the treatment of allergic diseases." (PMID 32038646, 2019).
amelogenesis imperfecta (3 papers, 2020 to 2023). Amelogenesis imperfecta (AI) represents a group of developmental conditions affecting the structure and clinical appearance of the enamel of all or nearly all the teeth in a more or less equal manner, and which may be associated with morphologic or biochemical changes elsewhere in the body. "On the other hand, it is interesting to note that patients with loss-of-function mutations in STIM1 and Orai1 also display an amelogenesis imperfecta phenotype, indicating that dysregulation of SOCE has a direct effect on bone/enamel mineralization." (PMID 32350310, 2020). "Based on several previous studies, patients with mutations in STIM1 and ORAI1 exhibit ectodermal dysplasia with amelogenesis imperfecta, which further confirms the significance of SOCE in enamel mineralization." (PMID 36935757, 2023). "In M-ABs, SOCE via the Orai1-Stim1 complex has been suggested to be the main calcium influx pathway, and patients with loss-of-function or null mutations in the STIM1 and ORAI1 genes present with a hypocalcified form of amelogenesis imperfecta." (PMID 36523561, 2022).
ankylosing spondylitis (3 papers, 2012 to 2021). An autoimmune chronic inflammatory disorder characterized by inflammation in the vertebral joints of the spine and sacroiliac joints. "For example, STIM1 polymorphisms have been shown to associate with the inflammatory index (erythrocyte sedimentation rate and C-reactive protein) in ankylosing spondylitis patients." (PMID 33348924, 2020).
channelopathies (3 papers, 2020 to 2025). "In comparison, relatively few of these channelopathies have been documented to specifically affect the immune system, and these channelopathies are principally due to recessive or biallelic variants in ORAI1, STIM1, or the recently described regulatory protein CRACR2A." (PMID 39270020, 2024). "Secondly, as exemplified in channelopathy caused by GOF mutations in Orai1 resulting in constitutive or increased SOCE independent of STIM1, therapeutic targeting of STIM1 might not be as efficient, taking into account that reduction of STIM1 might accelerate transition to HF." (PMID 33117812, 2020). "In-depth immunophenotyping and functional characterization, together with compelling clinical overlap with the non-immunological features seen in STIM1/ORAI1 channelopathies, such as ED and peripheral neuropathy, establish monoallelic missense variants in ITPR3 as a cause of syndromic CID." (PMID 39560673, 2025).
diffuse large B-cell lymphoma (3 papers, 2018 to 2022). "Latour el al have demonstrated that Orai1 and Stim1 could regulate diffuse large B cell lymphoma (DLBCL) cell motility and dissemination, promoting homing of tumor B cells to extra-nodal sites." (PMID 34579758, 2021).
experimental autoimmune encephalomyelitis (3 papers, 2020 to 2025). An autoimmune demyelinating disease of the central nervous system that is produced experimentally in animals by the injection of homogenized brain or spinal cord in Freund's adjuvant. "Experimental evidence demonstrated that stromal interaction molecule 1 (STIM1) expression was significantly downregulated in cortical neurons of mice with experimental autoimmune encephalomyelitis (EAE) induced by MOG35-55." (PMID 40661149, 2025). "They found that STIM1-conditional knockout mice exhibited worse disease outcomes and increased neuronal loss in experimental autoimmune encephalomyelitis (EAE), highlighting the crucial role of STIM1 in neuronal resilience." (PMID 39758424, 2024).
glioma (3 papers, 2013 to 2022). A benign or malignant brain and spinal cord tumor that arises from glial cells (astrocytes, oligodendrocytes, ependymal cells). "The authors report a novel splice variant of stromal interaction molecule 1, designated STIM1β, that is abnormally upregulated in glioma cells." (PMID 35076181, 2022). "A pro-proliferative role of STIM1 in vivo using U251 human glioma xenograft model in mice revealed that knocking down STIM1 in xenografts demonstrated a diminished growth." (PMID 30935064, 2019). "Both Orai1 and STIM1 knockdown induced sustained proliferation inhibition in glioma C6 cells by using siRNA technology, being the effect of Orai1 silencing more prominent than that of STIM1 silencing." (PMID 23578185, 2013).
Hyperglycemia (3 papers, 2017 to 2025). An increased concentration of glucose in the blood. "Downregulation of STIM1 was also observed in kidney sections from STZ-induced diabetic mice after long-term hyperglycemia." (PMID 29203863, 2017). "In view of our experiments revealing severely depleted ER Ca2+ stores and upregulation of Stim1 expression as UCD-T2DM lymphocytes progress to late-stage hyperglycemia, we explored the possibility that these signaling impairments may be associated with the development of an ER stress condition." (PMID 40723860, 2025).
leukemia (3 papers, 2020 to 2025). A malignant (clonal) hematologic disorder, involving hematopoietic stem cells and characterized by the presence of primitive or atypical myeloid or lymphoid cells in the bone marrow and the blood. "To verify the changes of STIM1-mediated calcium signaling during leukemia development, we measured constitutive capacities of calcium influx in Asic3-null leukemia bulk cells or LICs." (PMID 41392978, 2025). "Because CAMK1 activity is tightly regulated by the calcium signaling, we sought to understand how calcium signaling was affected by Asic3 deletion and found that the STIM1 level, a key mediator of calcium influx, was notably increased in LICs, as well as in YFP+ BM leukemia cells." (PMID 41392978, 2025).
muscular dystrophy (3 papers, 2020 to 2022). Muscular dystrophy (MD) refers to a group of more than 30 genetic diseases characterized by progressive weakness and degeneration of the skeletal muscles that control movement. "The enhanced muscle‐specific expression of STIM1 protein and a concomitant increase in sarcolemmal Ca2+ influx can alter the histological and biochemical characteristics of muscular dystrophy." (PMID 31833196, 2020). "Consistent with the idea that dysregulated activation of STIM1/Orai1-dependent SOCE promotes Ca2+-mediated muscle fiber degeneration in muscular dystrophy, STIM1 and Orai1 expression levels and SOCE activity were reported to be increased in dystrophin-deficient mdx mice." (PMID 35939054, 2022).
Obesity (3 papers, 2017 to 2026). Accumulation of substantial excess body fat. "One question arising from these observations is the nature of the mechanism underlying STIM1 dysfunction in obesity." (PMID 29243589, 2017). "To evaluate the activity of STIM1 proteins in obesity, we first validated antibodies for endogenous immunostaining." (PMID 29243589, 2017). "We also evaluated the time course of the defect in STIM1 trafficking during the development of obesity in mice." (PMID 29243589, 2017). "Based on these results we conclude that SOCE is critical for glucose and lipid metabolism and that increasing hepatic SOCE through overexpression of STIM1 is able to revert, at least in part, the deleterious impact of obesity on systemic glucose homeostasis." (PMID 29243589, 2017). "Further work identified that a small sugar molecule that is added onto STIM1 in obesity is behind its reduced ability to move accurately." (PMID 29243589, 2017). "A recent study reported the association of MYTIL (myelin factor 1-like), an early-onset obesity-related gene; APOL3 (apolipoprotein L3), lipid-transport and metabolism-associated genes; and STIM1 (stromal interaction molecule 1) involved in catty body weight gain." (PMID 32904540, 2020). "Thus, the obesity-related defect in STIM2 translocation was present but less dramatic than that observed for STIM1." (PMID 29243589, 2017). "Post-translational modification of STIM1 by phosphorylation and O-GlcNAcylation in obesity." (PMID 29243589, 2017). "In order to gain insight into mechanisms underlying this phenomenon, we considered the possibility that altered STIM1 post-translational modification could be involved in its defective translocation capacity in the context of obesity." (PMID 29243589, 2017). "Taken together these data indicate that increased modification of STIM1 by OglcNAc could, at least in part, underlie defective STIM1 translocation and reduced hepatic SOCE in the context of obesity." (PMID 29243589, 2017). "Therefore, we asked whether a reduction in STIM1 phosphorylation at these sites may explain its defective trafficking in obesity." (PMID 29243589, 2017). "Obesity leads to decreased SOCE and impaired STIM1 translocation in primary hepatocytes." (PMID 29243589, 2017).
oral cancer (3 papers, 2017 to 2026). "Three HNSCC cell lines, namely, TSCCA (oral cancer cell line) and Hep2 (laryngeal cell line) with high STIM1 expression levels and Tb3.1 (oral cancer cell line) with STIM1 expression level lower than previous two cell lines, were selected for in vitro study." (PMID 28494008, 2017). "siRNA-mediated knockdown of ORAI1 and STIM1 in Ca9-22 and OECM-1 oral cancer cell lines showed reduced proliferation, migration, and invasion of these cells." (PMID 35711942, 2022).
pancreatic ductal adenocarcinoma (3 papers, 2016 to 2024). An infiltrating adenocarcinoma that arises from the epithelial cells of the pancreas. "Interestingly, in pancreatic ductal adenocarcinoma (PDAC) IP3Rs and STIM1 are reorganised to the leading edge of migrating cells." (PMID 34460824, 2021).
prostate tumor (3 papers, 2015 to 2026). "It is observed that the growth of primary prostate tumors is linked to an increase in endoplasmic reticulum (ER)-plasma membrane (PM) junctions signaling, mediated by STIM1 and ORP5." (PMID 41677104, 2026). "Consistent with our observation in prostate tumor tissues with different Gleason scores, we also noticed that STIM1 expression was significantly lower in the more malignant cell line-PC3 than in the DU145 cells." (PMID 26257076, 2015).